CYP21A2 (cytochrome P450 family 21 subfamily A member 2)
Diseases named in the same sentence as CYP21A2 in open-access papers (continued):
Sharing a sentence is not in itself a finding about the gene and the disease.
lung squamous cell carcinoma (1 paper, 2024). "Five of the ten target drug genes are detected in lung squamous cell carcinoma tissues, whereas the expression of CCNA2, APOM, C4A, PKD2L1, and CYP21A2 was not very significant." (PMID 39175755, 2024).
melanoma (1 paper, 2021). A malignant, usually aggressive tumor composed of atypical, neoplastic melanocytes. "Meanwhile, the human melanoma line, which is shown to express CYP17, CYP21A2, POMC and CRH genes, could metabolize progesterone to corticosterone." (PMID 33529200, 2021).
mitral valve prolapse (1 paper, 2024). A fairly common and often benign valvular heart disorder characterized by redundancy or hooding of mitral valve leaflets so that they prolapse into the left atrium, often causing mitral regurgitation. "A partial deletion of CYP21A2 has been found in patients with mitral valve prolapse." (PMID 37938355, 2024).
thalassemia (1 paper, 2023). An inherited blood disorder characterized by a decreased synthesis of one of the polypeptide chains that form hemoglobin. "The findings manifest a lower frequency of HBB mutation than CYP21A2 mutations in the Turkish Cypriot population rising in Northern Cyprus, which can be the result of the premarital screening program for Thalassemia that started in 1984." (PMID 37895316, 2023).
tumor (11 papers, 2013 to 2026). "We acknowledge that we cannot determine that the corticotroph tumor CYP21A2 mutation that we observed in this patient contributed to either formation of and/or growth of her tumors." (PMID 40544420, 2025). "In summary, we report for the first time a double pituitary corticotroph tumor which harbored a G-protein coupled receptor (GP162) variant in one tumor and a novel ubiquitin specific protease (USP8) variant in the second corticotroph tumor in the setting of a background germline CYP21A2 variant." (PMID 40386408, 2025). "In summary, we report for the first time a double pituitary corticotroph tumor which harbored a G-protein coupled receptor (GPR162) variant in one tumor and a novel ubiquitin specific protease (USP8) variant in the second corticotroph tumor in the setting of a background germline CYP21A2 variant." (PMID 40544420, 2025). "As no cases with pathological CYP21A2 variations in both alleles could be identified, correlations between tumor size and basal levels of serum 17OHP and serum cortisol were examined in the entire population and not the two subgroups." (PMID 36545328, 2022). "Both CYP21A2 and CYP11B1 had discrepant dominant transcripts between the tumours, mirrored by a great range of total expression of these genes in the cohort, with some samples having very high expression and others very low." (PMID 31000732, 2019). "Notably, several key genes involved in steroid synthesis, including CYP11B2, CYP21A2, and HSD3B2, were significantly upregulated along the trajectories toward the tumor cell lineage." (PMID 40190189, 2025). "A possible explanation of the elevated 17OHP levels in these subjects is the intratumoral defects of steroidogenesis, i.e., an acquired defect of 21-hydroxylase in tumor cells alone without detectable pathological CYP21A2 variations on blood analysis." (PMID 36545328, 2022). "Bilateralism of the tumours, presence of Reinke crystals and expressions of synaptophysin, Inhibin α, CD56, androgen receptor, DLK1, INSL3, CYP11B1, CYP21A2 and MC2R have all been studied as potential markers, but none of these markers individually can reliably discriminate TARTs from LCTs." (PMID 29038332, 2017). "In addition, the tumor displayed positivity for steroidogenic enzymes CYP11B1 and CYP21A2." (PMID 24616772, 2013). "Histopathological analysis identified tumor regions with non-uniformly high expression of CYP17A1 and CYP21A2." (PMID 41594178, 2026).
genetic disorder (4 papers, 2013 to 2022). "POR polymorphisms may contribute this variability in clinical presentation with a given CYP21A2 defect, thus act as a secondary modifier gene, much like it occurs in other genetic disorders." (PMID 33666875, 2021).
cancer (3 papers, 2019 to 2021). A tumor composed of atypical neoplastic, often pleomorphic cells that invade other tissues. "KCNH2 and CYP21A2 promoter regions consisting of 10 (chr16: 15,042,868–15,043,044) to 12 CpG sites (chr12: 1,451,023–1,451,292) were drastically hypermethylated in cancer samples when compared with normal." (PMID 31569550, 2019). "These were chosen based on their gene expression patterns in cancer according to the literature survey: KRT5 and MMP7 for increased gene expression in cancer, KCNH2 for ambiguous expression in cancer, and CYP21A2 for unknown expression in BC." (PMID 31569550, 2019). "Since many anti-cancer drugs target enzymes from the steroidogenic pathway, we tested the effect of curcuminoids on cytochrome P450 CYP17A1, CYP21A2, and CYP19A1 enzyme activities." (PMID 31533365, 2019). "On the other hand, CYP21A2 and KCNH2, for which the expressions were not clearly investigated in human cancer, showed a heavily methylated promoter in cancer compared with a rarely methylated one in normal cells." (PMID 31569550, 2019).
CYP21A2 also shares sentences with these, for which no sentence is quoted: endocrine disorders (3 papers); autoimmune disorders (2); cystic fibrosis (2); Gaucher disease (2); spinal muscular atrophy (2); thymoma (2); acne (1); adenocarcinoma (1); adrenal tumors (1); adrenocortical tumors (1); adrenoleukodystrophy (1); albinism (1); Alpha-thalassemia (1); ankylosing spondylitis (1); Anosmia (1); Anxiety (1); autoimmune hemolytic anemia (1); autoimmune polyglandular syndrome type-1 (1); autoimmune thrombocytopenia (1); biotinidase deficiency (1); colitis (1); congenital hypothyroidism (1); Duchenne muscular dystrophy (1); electrolyte imbalance (1); Ellis-van Creveld syndrome (1); endometrial cancer (1); Evans syndrome (1); glycogen storage disease II (1); Hyperkalemia (1); metabolic disorders (1).
A further 22 diseases each share a sentence with CYP21A2 in 1 paper.